CDH1 (cadherin 1)
Diseases named in the same sentence as CDH1 in open-access papers (continued):
Sharing a sentence is not in itself a finding about the gene and the disease.
cancer (continued). "The analyzed genes in this work (SOX17, MYOD1, MAGI2, CDH1, AJAP1, MGMT, CDH13, and RASSF1A) participate in essential biological processes to maintain cell normality, and there is sufficient evidence for their protective role against the development of cancer." (PMID 34991696, 2022). "In absence of a germline CDH1 variant that is predicted to impair protein function, the patient was selected for WES analysis, but putative disruptive variants in cancer predisposition genes were not identified." (PMID 34075207, 2021). "Another important aspect of TGF-β–induced EMT in cancer cells and in vitro epithelial cell EMT models is the cadherin switch, which is characterized by increased CDH2 (N-cadherin) expression and decreased CDH1 (E-cadherin) expression." (PMID 33792620, 2021). "It represses the E-cadherin/CDH1 expression and subsequently promotes cancer metastasis." (PMID 34481526, 2021). "We note that CDH1 mRNA expression is maintained in SMARCA4 depleted cells, yet the protein is mislocalized and rapidly depleted in response to RSV infection, consistent with other studies in cancer." (PMID 33732255, 2021). "Snail-1, a transcriptional factor, silences CDH1 expression, promoting EMT and cancer invasiveness." (PMID 34206049, 2021). "Therefore, p16, CDH1, and MGMT methylation status can be suggested as a general methylation based panel marker for all cancers in Iranian patients." (PMID 33883026, 2021). "Non-MPM cancer cell lines showed higher levels of CDH1 mRNA expression (MKN45, HCC827, PC9, A549, and MCF7) when compared with healthy fibroblastic cells (Humofib)." (PMID 34638565, 2021). "In contrast, AS906 and AS914, which derived from carcinomas with sarcomatoid features and formed loose spheroids in culture, expressed ZEB1, SNAI2, CD44, and Vimentin, but negligible levels of EpCAM and E-Cadherin (CDH1)." (PMID 33941777, 2021). "We observed that CCRCC shows mesenchymal characteristics with high VIM and low CDH1 expression unlike other cancer types which reflects epithelial characteristics with high CDH1 and low VIM expressions." (PMID 32033228, 2020). "Furthermore, Twist1 expression positively correlates with EMT genes (CDH1, OCLN, TJP1, CDH2, FN1, SNAI1 and VIM) in various cancers." (PMID 32337580, 2020). "Combining with a previous study that ELK3 directly represses CDH1 expression in MDA-MB 231, this result indicates that CDH1 might be the main target of miR-200a/ELK3 axis to regulate migration and invasion of cancer cells." (PMID 32414208, 2020). "In addition, C7 was an enrichment cluster of squamous morphology cancer cell lines, mostly made of HNSC and ESCA and was characterized by high level of CDH1, CLDN7 and CAV1." (PMID 32874774, 2020). "In patients with heterozygous CDH1 PVs, gene inactivation of the second allele by somatic alterations leads to the development of DGC and LBC, whereas frequencies of other cancer types seem not to be affected." (PMID 33322525, 2020). "Furthermore, downregulation of LINC00261 altered the epithelial identity of PDAC cells by decreasing CDH1 levels and inducing an EMT-related transcription program that enhanced cancer cell invasion and migration." (PMID 32414223, 2020). "Interestingly, tumor suppressor gene CDH1 was upregulated upon HPRT1 knockdown, reiterating HPRT1’s role in cancer biology." (PMID 32532008, 2020).
cancer (continued). "Among all PMFs, tangeretin was the most effective in targeting cancer stemness and self-renewal ability, whereas scutellarein tetramethylether was shown to modulate EMT-related markers (increasing CDH1 and reducing ZEB1 and SNAI1 expression) and highly synergistically interact with 5-FU." (PMID 30717428, 2019). "The results showed that among the 60 cancer tissues, 41 tissues had no CDH1 expression or cytoplasm/membrane staining, with negative expression found in immunohistochemistry." (PMID 31317666, 2019). "Moreover, reduced EZH2 led to significantly reduced binding of LSD1, HDAC1, and DNMT1 to promoter regions of CDH1, CDKN1A, NEUROD1, and TUBB3, in agreement with increased transcription of these genes in cancer cells after EZH2 knockdown." (PMID 31130994, 2019). "In contrast, E-cadherin (CDH1), an invasion suppressor in many cancers, was upregulated." (PMID 31551414, 2019). "Altered expression profiles of epithelial E-cadherin (CDH1) and neuronal N-cadherin (CDH2) have often been observed in cancer cells, most notably in the context of the epithelial-to-mesenchymal transition (EMT) process that occurs during cancer progression." (PMID 31373305, 2019). "Further investigation of these genes, other known cancer-predisposing genes, and genes associated with DNA repair will aid in the disease management of families with hereditary diffuse gastric cancer without CDH1 pathogenic variants, whose risk of disease development is currently unknown." (PMID 29706558, 2018). "We conclude that TCF21 directly affects expression of CDH1, although possibly the cancer cell line we used does not have the intrinsic ability to incorporate significantly more E‐cadherin into the plasma membrane." (PMID 29080283, 2018). "BSA-GNPs in our study regulated CDK1 through up-regulation of Cdh1, so BSA-GNPs stabilizing microtubules may also lead to a potential cancer therapy." (PMID 30562921, 2018). "The coding genes affected by this epigenetic lesion cover all the molecular pathways related to cancer biology, such as DNA repair (BRCA1, MHL1 and MGMT), cell cycle (p16INK4a and p15INK4b), apoptosis (DAPK and TMS1) or cell adherence (E-cadherin and cadherin-11)." (PMID 30018746, 2018). "CDH1, FH, and CDKN1B are all involved in pathways in cancer." (PMID 29738475, 2018). "The results of this study suggest a role for the known cancer predisposition gene PALB2 in families with hereditary diffuse gastric cancer and no detected pathogenic CDH1 variants." (PMID 29706558, 2018). "Thus, ZEB1 is best known as a transcriptional repressor of CDH1 and inducer of EMT in breast and other carcinomas." (PMID 29744893, 2018). "Relative to other TNBC subtypes, claudin-low is characterized by a low expression of epithelial tight-junction claudin proteins, mucin 1 (MUC1), EPCAM and E-cadherin (CDH1), and high expression of epithelial-to-mesenchymal transition (EMT) markers, along with cancer stem cell (CSC) characteristics." (PMID 28235006, 2017). "For example, known disease genes BRCA2, CDH1, IDH1, CDKN2A, NME1 and FGFR3 frequently occurred at the top one in seven cancer types (including BC, GC, GBM, MB, MM, NB and OC), even though only two or three known-disease genes existed in NB, GBM and MB gene lists." (PMID 28076842, 2017). "Patients with CNV in KLF5, ZFHX3 and CDH1 had reduced cancer-specific survival, compared to patients without CNV in these genes (pairwise p = 0.028, 0.026, 0.044, respectively)." (PMID 28915599, 2017). "Besides miRNAs, the presence of CDH1a in tumors with lower levels of CDH1 could be attributed to other mechanisms, including a shift of transcription factors and/or other components of the transcription initiation machinery in favor of one transcript over the other in cancer cells." (PMID 27861150, 2017).
cancer (continued). "Previous evaluations obtained by qPCR method on intestinal GCs gave variable results with reports ranging from a clear decrease to a non-significant difference in CDH1 expression in cancer compared to the normal counterpart." (PMID 27861150, 2017). "In this study we evaluated CDH1 gene expression in the intestinal type by quantifying CDH1 canonical and CDH1a non-canonical transcripts in RNA from normal and cancer tissue samples by means of digital PCR (dPCR)." (PMID 27861150, 2017). "Moreover, pro-TAME with cell permeable activity disrupted the APC-Cdc20/Cdh1 interaction to reduce APC activation, leading to cell death in multiple cancer cell lines." (PMID 27626499, 2016). "Similar to CDH1, PCDH10 inhibits cancer cell motility and migration." (PMID 26871474, 2016). "Egger’s test of CDH1 methylation of cancer versus nonmalignant control showed that there was not any evidence of publication bias (P = 0.335)." (PMID 27067410, 2016). "Analysis of genes that are coexpressed with CDH1 (E-cadherin) in microarrays across 917 different cell lines from the cancer cell line encyclopedia demonstrates that the CD44 splicing protein, ESRP1, is one of the most highly correlated genes with CDH1 expression." (PMID 25850653, 2015). "CDH1 and IL1-Beta expression by cancer cells mediates the crosstalk between hMSCs and cancer cells." (PMID 26204886, 2015). "We observed that hMSCs formed niche-like structures when co-cultured with cancer cells expressing high levels of CDH1 and lacked IL-1β." (PMID 26204886, 2015). "In addition, our study identified other genes that are frequently hypermethylated in different types of cancer, such as RASSF1a, CDKN2A, hHML1, and CDH1." (PMID 25276247, 2014). "There were also gene sets related to cancer signaling pathways (MYC, STAT3, and CDH1) or genes moderately involved in cancer (IRF4, SOX4, and EZH2), as well as some associated with various aspects of cancer such as cell transformation, metastasis, and response to therapeutics." (PMID 25122487, 2014). "Loss of the expression of any members of the miR-200 family may play a critical role in the repression of CDH1 by ZEB1 and ZEB2 during the EMT, thereby enhancing migration and invasion during cancer progression." (PMID 24454732, 2014). "For AZD4547, the 20,000-fold difference in sensitivity to FGFR inhibitors suggests that FGF signaling is a critical driver to CDH1-initiated gastric cellular proliferation and this TKI represents a potential targeted therapy in diffuse subtype cancers harboring FGFR2 amplifications." (PMID 25315765, 2014). "Interestingly, the presence of HGF in the proximity of cancer cells, triggers KLF4 to inhibit CDH1 transcription." (PMID 24429391, 2014). "In both human cancer cell lines knockdown of ZEB1 resulted in elevated EPCAM and CDH1 expression." (PMID 23667256, 2013). "In these conditional double knockout mice, intramucosal and invasive cancers composed of signet ring cells were found from 6 to 9 months, while mice lacking only the CDH1 gene developed no cancers." (PMID 24216700, 2013). "Similarly to the regulation of cancer cell proliferation, TC adhesion and junction functions during placental development may be regulated by CTNNB1 and CDH1." (PMID 40150405, 2025). "Notably, the membrane protein E-cadherin (CDH1), which mediates homotypic cell–cell interactions and modulates epithelial–mesenchymal transition, a key feature of tumorigenesis–metastasis and cancer progression, is a substrate for MDM2." (PMID 39960347, 2025). "Thus, although CDH1 was expressed at high levels in noncancerous cells, F. nucleatum did not promote their proliferation, suggesting that certain changes specific to cancer cells are required for F. nucleatum to promote proliferation." (PMID 38698370, 2024).
cancer (continued). "This reduced penetrance may explain the lack of familial cancer related to CDH1, although to date there is no validated genotype–phenotype correlation to adapt follow-up recommendations." (PMID 37761816, 2023). "Two nephews decided to undergo CDH1 genetic testing for cancer prevention; both were negative." (PMID 37761816, 2023). "Of these, GO, and GSEA enrichment analyses showed that miR-340 or miR-185 combined with CDH1 overexpression existed in common enrichment pathways, such as glycolysis, MTORC1 signaling, steroid biosynthesis, peroxidase, and ubiquitination binding, which are closely related to cancer cell metabolism." (PMID 35784532, 2022). "Germline variants in CDH1 have also been reported as a cause of non-syndromic cleft lip and palate, and of familial Blephorocheilodontic (BCD) Syndrome, with or without an associated cancer risk." (PMID 34771713, 2021). "At this moment, the value of CDH1 testing in non-GC cancers other than BC may not be high, given the paucity of evidence." (PMID 34066044, 2021). "ECAD, a gene product of Cdh1, is a growth and invasion suppressor in some cancers but may also have bimodal oncogenic roles (reduction and increase in ECAD promote invasion, and metastasis, respectively) in other cancers." (PMID 34681626, 2021). "However, endoscopic detection of SRCC in CDH1 carriers is poor, and histological evaluation of surgical specimens demonstrates cancer foci in up to 45–60% of cases with a negative endoscopic evaluation." (PMID 32560361, 2020). "CDH1 repression and concomitant EMT transcription factors’ upregulation (e.g., SNAIL and SLUG), might then lead to a shift from epithelial to mesenchymal phenotype, allowing for increased cancer cell motility." (PMID 32344886, 2020). "In contrast, CDH1 H score and ROR risk were not independent variables for predicting patient survival, most probably because ROR score is indicative of cancer cell proliferation as well as hormonal signaling and cell differentiation." (PMID 32665033, 2020). "For these reasons, methylation of this gene has been investigated as a biomarker of the prediction of cancer development in 207 non-neoplastic patients and, together with CDH1, was found to be a promising liquid biopsy biomarker for early cancer diagnosis and prognosis prediction." (PMID 32752096, 2020). "In addition, the interaction between cadherin 1 (CDH1) and cadherin 2 (CDH2) may also have some beneficial effect for cancer cell colonization." (PMID 31753020, 2019). "The cancer cell microenvironment can also regulate E-cadherin expression, acting through hypoxia-inducible factor 1 (HIF-1), PPAR-γ, and a higher affinity of the transcriptional activators GRHL3 and HNF4A to the CDH1 enhancer regions, especially in secondary metastases." (PMID 31212809, 2019). "The low mutation prevalences, especially among those with diagnoses of regional or distant disease, suggest that somatic mutations in CDH1 and CTNNB1 are unlikely to explain a substantial proportion of cancer cell detachment from primary carcinomas originating at most anatomic sites." (PMID 29156750, 2017). "However, patients with CNV in specific genes, such as ZFHX3, KLF5 and CDH1, had reduced cancer-specific survival compared to patients without CNV in these genes." (PMID 28915599, 2017). "However, patients with copy number gains in KLF5, ZFHX3 and CDH1 had reduced cancer-specific survival, compared to patients without CNV in these genes ZFHX3 and CDH1, respectively (pairwise p ≤ 0.044)." (PMID 28915599, 2017). "A mesenchymal phenotype, characterised by low expression of E-cadherin (CDH1), high expression of vimentin (VIM) and high expression of EMT-inducing transcription factors, such as TWIST1, ZEB1, SNAI1 and SNAI2 moreover correlates with the expression of cancer stem cell markers CD44 and CD90." (PMID 29299154, 2017).
cancer (continued). "In general, ZNF703 may act as a transcriptional repressor and affect target genes which mediate various aspects of cancer pathophysiology, such as epithelial-mesenchymal transition, adhesion, motility, proliferation and cancer stem cell renewal, CDH1, cadherin-1, CTTND1, p120-catenin and TGFBR2." (PMID 27764785, 2016). "Our data also suggest that ML327 increases E-cadherin expression despite a paradoxical increase in binding of SNAIL to the E-cadherin promoter, and that SNAIL1 does not appear to be an important contributor to CDH1 transcriptional repression in these SW620 cancer cells." (PMID 26082441, 2015). "As KLF5 also directly activates transcription of CDH1, downregulation may indirectly play in favor of a progressive phenotype of certain cancer types, but not all." (PMID 24429391, 2014). "Therefore, correlations between CDH1, CDH2, and ZEB1 genes that have been described in cancer may also exist in early zebrafish development." (PMID 23667256, 2013). "Although the Log-rank tests allowed us to establish a positive correlation between CDH1 mRNA levels and cancer patient’s survival, the survival tests did not allow us to conclude whether CDH1 expression is functionally linked to cancer patient’s survival, showing another limitation of this study." (PMID 37189027, 2023). "Thus, most carcinoma samples examined did not exhibit a reduction in CDH1 mRNA levels." (PMID 37189027, 2023). "Among these proteins, MME, CDH1, APC, and CA9 have not been previously reported to be involved in anti-cancer regulations." (PMID 41567641, 2025). "In about 17% of familial GC tumors, CDH1 promoter hypermethylation has been detected, supporting the idea that an inherited propensity for epigenetic changes (perhaps triggered by H. pylori or other exposures) could be driving cancer in some familial non-hereditary case." (PMID 41097736, 2025). "H&E, E-cadherin (Cdh1) and CK19 stainings revealed differentiated and undifferentiated cancers regardless of genotype in our three different PDAC models." (PMID 36882420, 2023). "Plasma methylation of HPV genes, including L1, as well as promoter methylation of CADM1, CDH1 (promoter for E-cadherin), and CDH13 (cadherin-13), among others, readily distinguishes between cancer and benign/no disease controls." (PMID 38958745, 2023). "When analysing the CDH1 expression levels and the correlated sensitivity to PND-1186, we found that this relationship was present only in MPM cells and not in other cancers." (PMID 34638565, 2021). "The frequency of CDH1 deletions increases with tumor grade and is markedly higher among ERG fusion-negative cancers than among fusion-positive cancers." (PMID 31366128, 2019). "Although we did not observe obvious morphological changes in cancer cells after miR-182 overexpression, the EMT marker proteins, namely CDH1, CDH2 and Vimentin, were modestly regulated by miR-182." (PMID 27996004, 2016). "Western blot analysis confirmed that CLA carcinomas were Vimentin (VIM) positive, KRT19/CDH1 negative, while CLB carcinomas were VIM negative, KRT19/CDH1 positive." (PMID 26158412, 2015). "Most slides from cancer-free tissue lacked expression of CCND1, CD44, CDH1, EGFR, ERBB2, KIT, keratins, NOTCH1, PAK1, PTGS2, SNAI1, and VIM but showed staining of MUC1, HIF1A, NKX2-1, SFTPC, and STAT3, which were also found in AdCa." (PMID 23028920, 2012).